STAT3 (signal transducer and activator of transcription 3)
Diseases named in the same sentence as STAT3 in open-access papers (continued):
Sharing a sentence is not in itself a finding about the gene and the disease.
breast cancer (continued). "Our findings identify multiple functional pathways affected by MH in human breast cancer and highlight the IL-6/STAT3 signaling pathway as one of the earliest potential targets in this process." (PMID 28856117, 2017). "Here, the authors show that tyrosine kinases engage scaffold protein Shc1 to promote immunosuppression in breast cancer by simultaneously activating STAT3 immunosuppressive signals and impairing STAT1-driven anti-tumour immune responses." (PMID 28276425, 2017). "IL-6 is a direct regulator of breast CSC self-renewal and IL-6/JAK2/STAT3 pathway is more active in CD44(+)CD24(-/low) breast cancer cells compared with other tumor cell types and its inhibition blocks the growth of xenografts." (PMID 28270211, 2017). "This cytokine utilizes STAT3 as a transcriptional regulator of many genes that confer tumor-defining characteristics in breast cancer, including survival, proliferation, invasion, angiogenesis, and metastasis." (PMID 28856117, 2017). "Compared to MMTV‐Her‐2 transgenic mouse mammary tumors, H1047R tumors showed increased upregulation of Wnt/β‐catenin/Axin2, hepatocyte growth factor (Hgf)/Stat3, insulin‐like growth factor 2 (Igf‐2), and Igf‐1R pathways." (PMID 28296140, 2017). "The hGH/JAK2/STAT3 signaling transduction pathway has been identified as a critical signaling pathway in breast cancer and HCC." (PMID 28617312, 2017). "STAT3, as a transcription factor, is highly activated in breast cancer cells and promotes cancer cell growth." (PMID 29029463, 2017). "STAT3 is important for breast involution after weaning and considered a prognostic factor for breast cancer." (PMID 27861147, 2017). "In conclusion, both IL-6 and EGFR promote breast cancer through STAT3 abnormal activation and predict a poor prognosis." (PMID 27861147, 2017). "Here we found that CSE protein level is positively correlated with STAT3 protein expression in breast cancer, implying the involvement of STAT3 in upstream regulation of CSE expression." (PMID 29029463, 2017). "Our data indicate that miR-17-5p sensitizes MCF-7 breast cancer cells to Taxol-induced apoptosis and STAT3 is required for this sensitization." (PMID 28178652, 2017). "Taken together, these data suggested that CSE was the possible target gene of STAT3 in breast cancer." (PMID 29029463, 2017). "A recent study provided the first experimental evidence that STAT3 is essential for the establishment of immunosuppression during the earliest stages of breast cancer progression." (PMID 28276425, 2017). "CXCL12 induction of STAT3 phosphorylation has also been reported in other types of cancers, such as bladder cancer, breast cancer, and small cell lung cancer." (PMID 29379494, 2017). "Our finding supports that STAT3 was the potential treated target for breast cancer therapy, whereas STAT5A/5B/6 were potential prognostic markers for better survival of BC, providing more accurate prognosis." (PMID 28422733, 2017). "Loss of APC in the MMTV-PyMT mouse model increases activation of STAT3, which is constitutively activated in approximately 50% of breast cancer cell lines and tumor samples." (PMID 29262529, 2017). "CSE Function in breast cancer depends on the STAT3 signaling pathway, a regulator of critical cell functions including cell growth in a wide variety of human cancer cells via activating the expression of relative genes." (PMID 29029463, 2017). "In leptin-stimulated breast cancer cells, STAT3, extracellular signal-regulated kinase (ERK), and Akt activation has been demonstrated in several in vitro studies." (PMID 28930270, 2017). "Previous studies have shown that STAT3 can function as a modulator for CD44 expression in aggressive breast cancer cells and promote the CSC phenotype." (PMID 29036915, 2017). "TFF3 participated in cancer invasion metastasis in breast cancer through repression of CDH1 mediated by STAT3." (PMID 28070169, 2017).
breast cancer (continued). "Because human breast cancer cell line models were used to characterize the genome-wide binding patterns of STAT3 in TNBC, we next determined if these genome-wide binding patterns are also seen in primary tissue from TNBC tumors." (PMID 28030809, 2017). "HMLncs were enriched in malignant neoplasm of breast and focal adhesion, and LMLncs were enriched in mammary cancer, STAT3 pathway and Wnt signaling pathway." (PMID 28881636, 2017). "In the same line of evidence, it was shown that p-STAT3 was reported as a favorable prognosis marker in breast cancer, head and neck squamous cell carcinoma, and leiomyosarcoma." (PMID 28536310, 2017). "Here, we report that miR-17-5p-induced sensitization of breast cancer cells to paclitaxel-induced apoptosis requires STAT3." (PMID 28178652, 2017). "Western blots confirmed that STAT3 and pSTAT3 expression were higher in breast cancer tissue than in normal breast tissue." (PMID 28178652, 2017). "These clinical data also indicate that the miR-17-5p-STAT3 axis contributes to the development of breast cancer." (PMID 28178652, 2017). "Overall, these results indicate that the antitumor activity of PMM-172 is at least partially due to inhibition of STAT3 in breast cancer cells." (PMID 28588262, 2017). "STAT3 also contributes to migration in cancer cells, such as breast cancer, ovarian cancer, lung cancer, and gastric cancer, and inhibition of STAT3 would decrease the migration and invasion ability." (PMID 29226125, 2017). "In conclusion, nobiletin inhibited tumor angiogenesis by regulating Src/FAK/STAT3-mediated signaling through PXN in ER+ breast cancer cells." (PMID 28468300, 2017). "IL-6, a major cytokine present in the tumour microenvironment, can induce EMT and promote metastasis through the STAT3 signalling pathway in breast cancer, head and neck cancer and pancreatic cancer." (PMID 28198361, 2017). "qRT-PCR and WB results showed that both mRNA and protein levels of STAT3 were up-regulated in CSE-overexpressed human breast cancer tissues and human breast cancer cell line, which suggested that STAT3 is positively related to CSE expression." (PMID 29029463, 2017). "Studies have uncovered the potential role of STAT3 activation in glycolysis of cancer cells via HK2 pathway in breast cancer and ovarian cancer cells." (PMID 28445971, 2017). "They further suggest that increased STAT1 signalling in MT/Shc313F/313F mammary tumours is insufficient to promote immune suppression, because they retain elevated STAT3 activity." (PMID 28276425, 2017). "A number of signaling pathways besides STAT3 can enhance TICs in breast cancer including NOTCH signaling, Hedgehog signaling, and integrins." (PMID 29262529, 2017). "Our group has earlier shown that TFF3 increased STAT3 activity, which resulted in downregulation of E-cadherin, stimulated invasion and metastasis of ER+ mammary carcinomas." (PMID 29100386, 2017). "Although in normal mammary gland, Stat3 regulates cell death, breast cancer cells frequently become addicted to Stat3 and require Stat3 activity for survival." (PMID 27711075, 2016). "Our data showed that HER2 promotes radioresistance via STAT3-survivin regulation in HER2-positive breast cancers." (PMID 26755645, 2016). "IL-6 produced by tissue-specific fibroblasts promotes the growth and invasion of breast cancer cells through STAT3-dependent up-regulation of Notch-3, Jagged-1, and carbonic anhydrase IX." (PMID 26840088, 2016). "Stat3 is an oncogene expressed in many cancers including breast cancer, prostate cancer, lung cancer, head cancer, liver cancer, pancreatic cancer, and multiple myeloma." (PMID 27460364, 2016). "In our earlier studies, we observed that STAT3 is activated when AF1q is expressed in breast cancer cells." (PMID 27259262, 2016). "We examined the level of tyrosine phosphorylated (p)STAT3 and pSTAT5 in clinical samples from primary breast cancers and paired bone metastases." (PMID 27406745, 2016).
breast cancer (continued). "The pleiotropic cytokine IL-6 accelerates the progression of breast cancer in a variety of preclinical models through the activation of the STAT3 (signal transducer and activator of transcription 3) signaling pathway." (PMID 27602583, 2016). "MiR-124 overexpression in HER2 positive breast cancer cell line SKBR3 significantly reduced the activity of Stat3 signaling pathway compared with control transfection (P < 0.001)." (PMID 27815936, 2016). "We have recently shown that the aggressive breast cancer MDA-MB-231 cells as well as the interleukin-6 recombinant protein can activate breast stromal fibroblasts in a STAT3-dependent manner." (PMID 27248826, 2016). "6a is a pyrrolidinesulphonylaryl synthetic molecule that suppresses IL-6 signaling in the MDA-MB-231 breast cancer cell line via selective inhibition of STAT3 phosphorylation and transcription." (PMID 26840088, 2016). "Further evidence revealed that the growth of HER2-positive breast cancer in vivo was dependent on the HER2/IL-6/STAT3 signaling pathway." (PMID 26840088, 2016). "It inhibits STAT3 dimerization, DNA binding, and STAT3-activated luciferase reporter activity in breast cancer cells." (PMID 27166190, 2016). "Irina Daurkin and colleagues reported that TAMs regulate murine breast cancer stem cells through a novel paracrine EGFR/Stat3/Sox-2 signaling pathway." (PMID 27703219, 2016). "Leptin upregulation of VEGF/VEGFR-2 is mediated by leptin-induced JAK/STAT3-Notch expression while also showing that leptin regulation of VEGF/VEGFR2 in breast cancer involves the activation of Src and Gbr2/Gab2/STAT3, suggesting crosstalk with Rho-GTPases." (PMID 27472371, 2016). "In this study, we bioinformatically predicted a role for Stat3 in Myc induced mammary tumors and tested it using mouse models." (PMID 27589562, 2016). "Of the members of the STAT family, STAT3 has been shown to be the most important for breast cancer progression." (PMID 27602583, 2016). "A role for Signal Transducer and Activator of Transcription 3 (STAT3) in sustaining pluripotency and self-renewal capacity has been described in ESCs as well as CSCs, notably glioblastoma stem cells, breast cancer stem cells, and prostate cancer stem cells." (PMID 26880966, 2016). "Stat3 is constitutively activated in breast cancer and activation of Stat3 is stimulated by cytokines and growth factors." (PMID 27589562, 2016). "Induction of IL-6 production by the adipokine leptin in breast cancer amplifies STAT3 signaling, and phosphorylation of STAT3 is significantly reduced by IL-6 neutralizing antibodies." (PMID 26840088, 2016). "Other studies have suggested that tyrosine 705 phosphorylation of STAT3 is a marker of good prognosis, at least in breast cancer." (PMID 26768588, 2016). "With respect to gene expression control, granulin is known to be able to activate PKC pathway and Toll-like receptor 9 signaling or interact with transcriptional factor such as STAT3 in breast cancer cells." (PMID 27598941, 2016). "In a conclusion, EMMPRIN plays important roles in breast cancer stem like cells influenced by fibroblasts and cancer cells, inhibits miR-106a/b expression which down-regulates STAT3 and HIF-1α." (PMID 27325313, 2016). "To this end, first we examined the expression levels of the transcription factors such as STAT3, NF-κB and Fra-1 that are frequently associated with EMT signaling in breast cancer cells after fractionated irradiation." (PMID 27462787, 2016). "And the tyrosine 23 phosphorylation of Anxa 2 promotes the proliferation and invasion of human breast cancer cells, also via upregulating the STAT3 phosphorylation." (PMID 27274723, 2016). "Together, these in vitro and in vivo results suggest that miR-124/Stat3 regulation is a key factor in radiotherapy response of HER2-positive breast cancers." (PMID 27815936, 2016).
breast cancer (continued). "The transcriptionally amplified PDGF-B regulated by AF1q accelerated activation of the PDGFR-Src kinase cascade, driving persistent STAT3 activation (pYSTAT3) in breast cancer cells." (PMID 27259262, 2016). "Another study revealed that combined treatment of curcumin with epigallocatechin gallate reduced the CSCs population in breast cancer cells via inhibiting STAT3 phosphorylation, retaining STAT3-NF-κB interaction and inducing apoptosis in CSCs." (PMID 27338343, 2016). "Because MDA-MB-231LN breast cancer cell lines are known to possess constitutively activated Src kinases, we examined STAT3 phosphorylation levels in MCF10a normal human breast epithelial cells with enforced or suppressed AF1q expression." (PMID 27259262, 2016). "Stat3 is an oncogene and constitutively activated Stat3 has been found in many types of cancer, including breast cancer." (PMID 27460364, 2016). "A recent study further showed that STAT3 mediates cell surface HSPA5-induced human breast cancer MCF-7 cells migration." (PMID 27034162, 2016). "Forced miR-124 expression in HER-2 positive breast cancer cell line SKBR3 resulted in down-regulation of Stat3 expression, inhibition of Stat3 signaling pathway, and enhanced sensitivity to irradiation." (PMID 27815936, 2016). "Fascin expression is induced by a variety of cytokines such as interleukin-6 (IL-6) and oncostatin M via transactivation of signal transducers and activators of transcription 3 (STAT3) in breast cancer cells." (PMID 27036017, 2016). "STAT3 activation has been reported in nearly 70% of solid and haematological tumours, including gastric cancer, breast cancer, colorectal cancer, lymphomas, multiple myeloma, and leukaemia." (PMID 27052330, 2016). "During the investigation of the molecular mechanism underlying EMMPRIN promoting breast cancer stem-like cells, SUM102 and BT474 cells were treated with human recombinant EMMPRIN (hrEMMPRIN) and we found that STAT3 was activated." (PMID 27325313, 2016). "Radiation-induced activation of STAT3 was inhibited by HER2 depletion in HER2-positive SKBR3 and MDA-MB453 breast cancer cells, as determined by the decreased level of phosphorylated STAT3 and survivin." (PMID 26755645, 2016). "Immunohistochemical analysis of total and ph-STAT1, and STAT3 were performed on tissue microarray of 384 breast cancer specimens." (PMID 27769057, 2016). "In breast cancer xenografts, IL-6 activates STAT3 by binding to its receptor (gp130) and directly stimulates breast CSC self-renewal." (PMID 26980947, 2016). "MTA1 has been reported to promote lung metastasis of breast cancer by stimulating STAT3 transcription and the expression of STAT3 target genes." (PMID 26968810, 2016). "The interdependent activation of two inflammatory signaling pathways, NF-kB and STAT3, in this study resulted in increased breast cancer cell aggressiveness and hormone-independent tumor growth." (PMID 27609180, 2016). "In breast cancer, the constitutive activation of STAT3 was shown to attenuate metformin-induced apoptosis." (PMID 27052330, 2016). "Depletion of HER2 by siRNA sensitized HER2-positive breast cancer cells to irradiation by decreasing STAT3 activity and survivin, a STAT3 target gene, expression in HER2-positive breast cancer cells." (PMID 26755645, 2016). "Our results illustrated that EMMPRIN has an important role in breast cancer stem-like cells by activation STAT3/HIF-1α through interaction with cancer cells and fibroblasts." (PMID 27325313, 2016). "Recent studies have suggested that Stat3 activation is important for the tumorigenic ability of cancer stem cells in breast cancer." (PMID 27460364, 2016). "Ten studies have examined the prognostic value of STAT3 in breast cancer, using either total STAT3 or phosphorylated STAT3 (ph-STAT3)." (PMID 27769057, 2016).
breast cancer (continued). "Src is required for progestin-induced and basic fibroblastic growth factor-induced STAT3 phosphorylation in breast cancer cells and human umbilical vein endothelial cells, respectively." (PMID 26956044, 2016). "It induces caspase dependent extrinsic apoptosis in human epidermal growth factor receptor 2 (HER-2) over expressing BT-474 breast cancer cells through inhibition of signal transducer and activator of transcription 3 (STAT3) signaling." (PMID 27877185, 2016). "IL-6 is elevated in HER2-positive breast cancer where IL-6 activated STAT3 and induced an autocrine loop of IL-6/STAT3 expression." (PMID 26840088, 2016). "Treatment with S3I-201 abolished Stat3 phosphorylation and significantly increased radiation-induced cell death, supporting the fact that Stat3 is important in mediating radiotherapy resistance in HER2-positive SKBR3 breast cancer cells." (PMID 27815936, 2016). "IL-6/STAT3 signaling has been shown to be essential for the paracrine activity of senescent breast cancer cells." (PMID 27489164, 2016). "Knockdown of miR-27b augmented Nischarin (NISCH) and suppressor of tumorigenicity 14 (ST14) expression in human breast cancer, down-regulated STAT3, c-myc and cyclin D1 in glioma." (PMID 26910911, 2016). "MTA1 enhances lung metastasis of breast cancer by upregulating STAT3 transcription, which promotes cell survival, angiogenesis, invasion and metastasis." (PMID 26968810, 2016). "The targets of the top luminal miRNAs were activators of EMT (ZEB1, ZEB2) and basal subtype transcription (IL-6, EGFR, STAT3), whereas the targets of the top basal miRNAs were involved in adipogenesis pathways and luminal breast cancer (ERBB2, ERBB3)." (PMID 27845906, 2016). "A previous study also demonstrated that miR-143 and STAT3 regulated the expression of hexokinase 2 in breast cancer cells." (PMID 27767041, 2016). "Taken together, these results suggested that HER2 enhances radioresistance by activating STAT3 signaling in HER2-positive breast cancer cells." (PMID 26755645, 2016). "Consistent with the mammary gland histological findings, Myc Stat3 CKO mice developed mammary tumors significantly more quickly than Myc transgenics (p<0.001)." (PMID 27589562, 2016). "We propose that careful classification of a patient’s breast cancer subtype is central to effectively targeting STAT3/5 as a therapeutic means of treating breast cancer, particularly given that xCT is emerging as an important biomarker of aggressive cancers." (PMID 27513743, 2016). "Activation of JAK2/STAT3 pathway preferentially promotes the self-renewal of C24−CD44+ breast cancer stem cells." (PMID 26883017, 2016). "In SUM149 triple negative breast cancer cells and in BT474 ERBB2+ breast cancer cells expression of an activated form of STAT3; an activated form of AKT; or an activated form of MEK1 inhibited the lethality of [ruxolitinib + MMF] treatment (p < 0.05)." (PMID 26981780, 2016). "This suggests a possible role for EZH2 in promoting breast cancer stem cells through the methylation and activation of STAT3." (PMID 27764181, 2016). "Consistent with previous findings, the inhibition of Stat3 in our breast cancer mouse model resulted in a lower metastasis rate." (PMID 27460364, 2016). "Together, these results suggested that Stat3 was a direct target of miR-124 in HER2-positive breast cancer cells." (PMID 27815936, 2016). "IL-6 secreted from senescent mesenchymal stem cells can increase the proliferation and migration of breast cancer cells by induction of STAT3 phosphorylation." (PMID 26840088, 2016). "Synergy of leptin/STAT3 with HER2 receptor induces tamoxifen resistance in breast cancer cells through regulation of apoptosis-related genes." (PMID 27472371, 2016). "Consistently, chemical inhibitor of Stat3 also sensitized HER2-positive breast cancer cells to irradiation." (PMID 27815936, 2016).